HAUS2 (HAUS augmin like complex subunit 2)
Description:
Contributes to mitotic spindle assembly, maintenance of centrosome integrity and completion of cytokinesis as part of the HAUS augmin-like complex.
Synonyms: Cep27; C15orf25; FLJ10460; HsT17025
Tractability: PROTAC: ubiquitination databases record sites on it.
Gene: Protein-coding gene on chromosome 15 (42,548,828 to 42,569,994, forward strand). Ensembl gene ENSG00000137814.
Subcellular location: Cytoplasm, cytoskeleton, microtubule organizing center, centrosome; Cytoplasm, cytoskeleton, spindle
Subcellular location (Human Protein Atlas): Cytosol; Nucleoplasm; Centrosome
Pathways (Reactome):
Cell Cycle: AURKA Activation by TPX2; Loss of Nlp from mitotic centrosomes; Loss of proteins required for interphase microtubule organization from the centrosome; Recruitment of NuMA to mitotic centrosomes; Recruitment of mitotic centrosome proteins and complexes; Regulation of PLK1 Activity at G2/M Transition
Organelle biogenesis and maintenance: Anchoring of the basal body to the plasma membrane
Gene Ontology:
Molecular function: protein binding
Biological process: centrosome cycle; spindle assembly; regulation of microtubule nucleation; microtubule organizing center organization
Cellular component: centrosome; HAUS complex; mitotic spindle microtubule; cytosol; spindle; spindle microtubule
Genetic constraint (gnomAD): Loss-of-function variants: 0 observed, 0.35 expected, observed/expected ratio (o/e) 0, 90% interval 0 to 1.86. That is too few expected variants to judge how well the gene tolerates losing a copy. Missense variants: 51 observed, 30.04 expected, observed/expected ratio (o/e) 1.7, 90% interval 1.34 to 1.95. Synonymous variants: 26 observed, 16.29 expected, observed/expected ratio (o/e) 1.6, 90% interval 1.15 to 1.94.
Homologues: Orthologues: chimpanzee HAUS2 (100% identical), macaque HAUS2 (97% identical), rabbit HAUS2 (84% identical), pig HAUS2 (82% identical), guinea pig HAUS2 (77% identical), rat Haus2 (72% identical), mouse Haus2 (70% identical), dog HAUS2 (64% identical), tropical clawed frog haus2 (45% identical), zebrafish haus2 (30% identical).
Diseases named in the same sentence as HAUS2 in open-access papers:
HAUS2 is named in the same sentence as 3 diseases in open-access papers, as found by Europe PMC text mining. Sharing a sentence is not in itself a finding about the gene and the disease. The quoted sentences say what the papers report.
glioblastoma (1 paper, 2022). The most malignant astrocytic tumor (WHO grade IV). "HAUS augmin-like complex subunit 2 (HAUS2) interacts with the γ-tubulin ring complex and is involved in spindle assembly, and one of its paralogs are associated with glioblastoma." (PMID 35559016, 2022).
HAUS2 also shares sentences with these, for which no sentence is quoted: Sepsis (2 papers); tumor (1).